CCL19 (C-C motif chemokine ligand 19)
Diseases named in the same sentence as CCL19 in open-access papers (continued):
Sharing a sentence is not in itself a finding about the gene and the disease.
tumor (continued). "The results indicated that CCL19 expressed by tumor cells had a chemotactic effect on CCR7-positive T cells." (PMID 34527749, 2021). "The expression of CCL2 correlated with all of the other chemokines (also in tumor-adjacent tissue), while CCL19 was the least correlated gene." (PMID 34885960, 2021). "IL‐7 and CCL19 are crucial for T‐cell zone maintenance in lymphoid organs and T cells expressing IL‐7 and CCL19 exhibited great tumor clearance capacity." (PMID 34766142, 2021). "In particular, CCL19 is a chemotactic factor involved in recruiting CD4+CD25+CD69- T-regs to zones of T cell infiltration in the tumor micro-environment." (PMID 34298673, 2021). "Analysis of the tumor EV-educated macrophages (TEMs) showed secretion of a variety of factors including CXCL1, CTLA-4, IFNG, OPN, HGF, TGFB, and CCL19 capable of remodeling the surrounding tumor stroma and immune infiltrate." (PMID 34298673, 2021). "Among them, CCL19 which is as an important member of chemokine-mediated signaling pathway has demonstrated that its expression level in tumor FSC is related to the degree of immune cell infiltration of CD8 + T cells and tumor accumulation (29391257)." (PMID 34603645, 2021). "Compared to normal tissue from non-cancer patients, the CCL3, CCL4 and CXCL2 expressions were upregulated in both tumor and tumor-adjacent tissue, while CCL19 was upregulated solely in tumor-adjacent tissue." (PMID 34885960, 2021). "Unlike with other chemokines, there seems to be a consensus on the anti-tumor role played by MIP-3β/CCL19, at least in CRC." (PMID 34885960, 2021). "In this study, the therapeutic effect was increased by the intratumoral injection of AAV-CCL19 to make tumor cells express CCL19 and recruit and promote memory CAR-T cells to infiltrate into the tumor interior." (PMID 34527749, 2021). "In HEVhigh tumours compared with HEVlow tumours, gene profile of HEVs has shown upregulation of genes encoding lymphoid chemokines including chemokine (C-C motif) ligand (CCL) 19 (CCL19), CCL21, and CXCL13 as well as T-cell homing receptors (CCR7 and LSEL)." (PMID 33917287, 2021). "Adachi and colleagues also showed that IL-7 and CCL19 co-expressing CAR-T cells become differentiated into central memory CAR T cells with superior tumor-infiltrating capacity and higher persistence rate in a P815-hCD20 (mastocytoma) mouse model." (PMID 34721401, 2021). "Subsequently, the secretion of TNFα and CCL19 induces the infiltration and maturation of DCs in tumor tissues, thus inhibiting NSCLC progression." (PMID 34660305, 2021). "The mRNA expression of CYP1A1 (p = 0.002), CCL20 (p = 0.047), p19 (p = 0.029), CCL19 (p = 0.013), IL-36γ (p = 0.0076), and IL-17 (p = 0.0035) was significantly decreased in tumor from AhR-(fl/fl) Krt5-(Cre) mice compared with wild type mice." (PMID 33178182, 2020). "Mature DCs are recruited into the tumor niche by the CCL19/MIP-3β and CCL21/secondary lymphoid tissue (SLC) chemokines." (PMID 33114763, 2020). "Pre-clinical studies have demonstrated that CCL19/CCL21 producing lymphatic endothelial cells can actively guide the chemotactic migration of CCR7-expressing tumor cells." (PMID 32340161, 2020). "CCL19 is also an adjuvant for DNA vaccination, and it can improve the body's resistance to tumor cells." (PMID 32775427, 2020). "CCL19 attracts mDCs and lymphocytes expressing CCR7 in T cell-rich areas, and thereby helping DCs meet tumor-associated antigen-specific T cells." (PMID 31991604, 2020). "CXCL12 is expressed by many tumor types and supports tumor survival, and, together with CCL19/21, also favors metastatic spread." (PMID 32272610, 2020). "An active mechanism of tumor dissemination via lymphatics involves the chemokines CCL21 and CCL19, which are secreted by tumor cells." (PMID 33262763, 2020).
tumor (continued). "The mRNA levels of Ccr7, Mmp9, c-Fos (Fos proto-oncogene, AP-1 transcription factor subunit), c-Jun (Jun), Ccl19 (C-C motif Chemokine Ligand 19) and Ccl21 were significantly reduced in tumor of CRE treated mice." (PMID 30781353, 2019). "The study also showed that lymphodepletion before CAR T cell injection decreased efficacy, suggesting that IL-7 and CCL19 recruited endogenous anti-tumor TILs as well." (PMID 30804938, 2019). "Results revealed that the average volume and weight of tumor nodules were increased in SW620/sh-CCL19 groups and decreased in SW1116/CCL19 groups and CT26 + rmCCL19 groups compared with control groups." (PMID 30250188, 2018). "From these data, two miRNAs (miR-20a and miR206) were up-regulated and three miRNAs (miR-17, miR-19a, miR-200b) were down-regulated in the CCL19 overexpression tumor cell supernatants treated HUVECs." (PMID 30250188, 2018). "Next, we analyzed association between CCL19 expression and tumor MVD, then we found that CCL19 was significantly negativly correlated with tumor MVD." (PMID 30250188, 2018). "CCR7 plays a role in the migration of tumor cells such as immune cells into lymphoid organs through binding to its only two ligands CCL19/CCL21." (PMID 30233771, 2018). "Immunohistochemistry assay was conducted to detect the expression of CCL19 in 78 pairs of CRC tumor and adjacent normal tissues." (PMID 30250188, 2018). "CCL19 was significantly overexpressed in tumor tissues (88.71%; 55/62) than in normal counter parts (37.10%; 23/62, P < 0.001)." (PMID 29088748, 2017). "The systemic or intraperitoneal administration of a recombinant vaccinia OV (vvDD) expressing the chemokine CCL-19 was found to result in enhanced anti-tumour effects in syngeneic mouse tumour models." (PMID 29157300, 2017). "Tumor cells are guided into the lymphatics by chemokine gradients, in which CCL19 and CCL21 are key players in metastatic dissemination of malignant cells via the lymphatic system." (PMID 28036019, 2016). "C-C chemokine receptor 7 (CCR7) expression levels, the marker of migrating DCs, in spleen DCs and tumor drLN and its ligands C-C motif ligand 19 (CCL19) and CCL21 in spleen were substantially increased by ascophyllan." (PMID 27008707, 2016). "Through global transcriptome analysis, immune-related functions were found to be key regulators in the spleen associated with tumor progression as a function of age with CD2, CD3ε, CCL19, and CCL5 being the key molecules involved." (PMID 26497558, 2015). "Other studies have explored the possibility of using oncolytic vaccinia virus to express chemokines such as CCL5 and CCL19 to enhance the therapeutic effect by increasing T cell and dendritic cell infiltration into tumor tissues." (PMID 25460506, 2015). "Intratumoral injection of both CCL19 and IL-7 slowed tumor growth and completely eradicated lung tumors in 5/6 mice." (PMID 24762633, 2014). "Expression of CCL5, CCL3, and CCL19 by OVs enhances chemotaxis of immune cells within the tumor and improves overall therapeutic benefits in vivo." (PMID 24967214, 2014). "In this study, transfer of T lymphocytes from CCL19 treated tumor-bearing mice conferred the anti-tumor therapeutic efficacy of CCL19 to naive mice." (PMID 24810425, 2014). "High intra-tumoral levels of CCL20 result in the accumulation of immature CCR6+ DCs within the tumor bed, whereas high peri-tumoral levels of CCL19 promote the accumulation of mature CCR7+ DCs preferentially to the tumor margin." (PMID 24339824, 2013). "Again, mice injected with both Her2/neu pDNA and CCL19 pDNA had substantially improved tumor protection (58% versus 22% tumor-free incidence)." (PMID 24967094, 2013). "Co-expression of pDNA encoding CCL19 and tumor antigen resulted in enhanced Th1 immune response and increased CD8+ T cell infiltration in the tumor bed." (PMID 24967094, 2013). "CCL19/MIP3β expression on tumor cells and DC had a different distribution among tumor samples were therefore analysed as two distinct biomarkers." (PMID 21624121, 2011).
tumor (continued). "CCR6 was detectable in tumor cells, while CCL19 was expressed by both tumor cells and stroma-infiltrating cells exhibiting a dendritic morphology." (PMID 21624121, 2011). "The reduced tumour burden in CCL19-treated mice was accompanied by extensive lymphocyte as well as DC infiltrates of the tumour sites." (PMID 16598185, 2006). "Mice treated with CCL19 had a marked reduction in pulmonary tumour burden (130±15 μm2) as compared with diluent-treated control mice (495±40 μm2) (P<0.001)." (PMID 16598185, 2006). "CCL19 treatment led to a marked reduction in tumour burden with extensive mononuclear infiltration of the tumours compared to diluent treated controls." (PMID 16598185, 2006). "The tumour sites of CCL19-treated mice revealed significant increases in IFN-γ, CXCL10/CXCL10/IP-10, CXCL9/CXCL9/MIG, and GM-CSF." (PMID 16598185, 2006). "Based on the capacity of CCL19 to facilitate co-localisation of both DC and T cells, we and others are evaluating the capacity of CCL19 to reverse tumour-mediated immune suppression and orchestrate effective cell-mediated immune responses." (PMID 16598185, 2006). "CCL19 injected into the axillary lymph node region evidenced potent antitumour responses, with reduced tumour burden as compared to mice receiving diluent control injections." (PMID 16598185, 2006). "CCL19 has potent systemic antitumour responses in vivo; it enhances the frequency of T-cell subsets and DCs at the tumour sites; it promotes type 1 cytokine and antiangiogenic chemokine release as well as a decline in the immunosuppressive cytokine TGF-β." (PMID 16598185, 2006). "In contrast, CCL19-treated mice had significantly smaller tumour nodules with extensive lymphocytic infiltration." (PMID 16598185, 2006). "That rPR8-CCL19 exhibited dual surprising capabilities: efficient replication within CRC cells, which led to tumor cell lysis; and these CCL19 expressions could recruit and activate lymphocytes for remodeling TME." (PMID 41446741, 2025). "As a chemokine, CCL19 directs activated CD8 T cells to migrate toward tumor sites." (PMID 40895068, 2025). "Additionally, CCL19 augments lymphangiogenic potential by stimulating LEC sprouting and vessel maturation, facilitating tumor-associated lymphangiogenesis." (PMID 40895068, 2025). "Moreover, studies have shown that CAR-T cells engineered to co-secrete IL-7 and CCL19 (7 × 19 CAR-T cells) exhibit superior tumor suppression, proliferation capacity, and tumor infiltration in HCC xenograft models." (PMID 40051497, 2025). "However, the upregulation or downregulation of CCL19 in cancer varies depending on the specific tumor microenvironment and remains uncertain." (PMID 40072746, 2025). "In BC, CCL19, as a novel prognostic chemokine, exhibits aberrant high expression, which not only recruits immune cells to create a tumor microenvironment that inhibited for tumor growth and metastasis but also suppress tumor cell migration and invasion." (PMID 40895068, 2025). "Moreover, CCL19 has been shown to modulate the BC immune microenvironment through interactions with tumor-infiltrating immune cells (TICs)." (PMID 40895068, 2025). "Hence, based on the current findings, we propose a schematic representation to depict the potential mechanisms through which IL-15 and CCL19 augment the functionality of CAR-T cells within the tumor microenvironment." (PMID 40177238, 2025). "CCL21 and CCL19 expressed in several stromal cells may exhibit antitumor activities at primary tumor sites because these chemokines induce the recruitment of CCR7-expressing activated dendritic cells to the tumor site." (PMID 40028039, 2025). "However, studies have also shown that certain fibroblast types such as Ccl19+ fibroblasts, can have anti-tumor function potentially by supporting CD4+ T and B/plasma cell function." (PMID 40568084, 2025).
tumor (continued). "In conclusion, the incorporation of IL-15 and CCL19 into CAR-T cells emerges as a promising strategy to elevate the anti-tumor efficacy of CAR-T cell therapy, positioning 15 × 19 CAR-T cells as a potential breakthrough for enhancing the application of CAR-T therapy in solid tumors." (PMID 40177238, 2025). "A study was conducted to genetically engineer TCR-T cells (7 × 19 P1A T) to express both IL-7 and CCL19, which resulted in complete tumour regression and prolonged survival in half of the mice after 7 × 19 P1A T treatment in a murine mast cell tumour P815 model." (PMID 38675377, 2024). "Furthermore, CCL19 administration alone in a model of colorectal cancer disrupted angiogenic programs, resulting in decreased tumor size and metastasis." (PMID 38786066, 2024). "P1A tumor antigen-specific TCR-T cells which produced IL7/CCL19, showed noticeably increased anticancer effects and produced long-term memory responses by enhancing the infiltration of dendritic cells and T cells in tumor tissues, including both endogenous T cells and transplanted P1A T cells." (PMID 38693513, 2024). "We found that IL7/CCL19-producing CAR-T cells generated from the patient’s PBMC showed potent therapeutic effects against the solid cancer model established by inoculating organoids from the autologous tumor tissue." (PMID 39240078, 2024). "CCL19 exhibited high expression levels within intra-tumor immune infiltration." (PMID 39505867, 2024). "Additionally, we observed the accumulation of DKK1+ tumor cells within the tumor area in immune-exclusion samples, particularly at the tumor boundary, which inhibited the infiltration of CCL19+ fibroblasts and plasma cells into the tumor area." (PMID 39505867, 2024). "While the injected CAR-T cells showed a significant effect, which was dependent on IL-7 and CCL19 secretion, the depletion of host T-cells abrogated the anti-tumor effects, suggesting co-operation between adoptively transferred and native T-cells in facilitating tumor rejection." (PMID 38339310, 2024). "Indeed, quantitative analysis of the DLN lysate on day 2 after tumor IR (which corresponds to day 9 after neoadjuvant DLN IR) revealed a marked reduction of CCL19 in the DLNs irradiated in both the concomitant and neoadjuvant settings (left)." (PMID 38951172, 2024). "Interestingly, increased expression of CCL19, CXCL9 and CXCL10 is associated with recruitment of immature CD56bright NK cells with low perforin content in the tumor microenvironment (TME), which is thought to protect tumor cells from NK cells." (PMID 40809150, 2024). "Similarly, we were unable to thoroughly investigate the role of the covalent link between CCL19 and the cancer neoepitopes as delivering them together -either fused in a single plasmid or two separate ones- effectively prevented tumor development." (PMID 37720215, 2023). "The observed increase in the CCL19 expression may promote IFN‐γ‐dependent anti‐tumor defense by inducing the homing of CCR7+ T cells and DCs." (PMID 37675835, 2023). "Notably, in OV, the content of CCL19 in normal tissues was significantly higher than that in tumor tissues, hinting at a potential role for reduced CCL19 in the development of OV." (PMID 37944262, 2023). "Elevated CCL19 levels in a tumor result in anti-cancer TIL infiltration." (PMID 36755259, 2023). "This implies that CCL19-activated tumor microenvironments might inhibit the activity of these immune-effective cells in cancers." (PMID 37944262, 2023). "HERV-H env ISD was essential for tumor cell immune evasion, metastatic invasion, and adhesion, which could induce tumor cell epithelial-mesenchymal transition, increase CCL19 factor expression, recruit and expand pluripotent immunoregulatory CD271 cells." (PMID 37342563, 2023). "Histological observation showed that the content of CCL19 in normal tissues was significantly higher than that in tumor tissues, indicating that short of CCL19 may contribute to the occurrence of BRCA and OV." (PMID 37944262, 2023).
tumor (continued). "However, the situation in BRCA samples was distinct, with CCL19 expression levels in normal tissues being lower than those in tumor tissues." (PMID 37944262, 2023). "For example, CCL19-producing fibroblastic stromal cells could suppress tumor growth in NSCLC through facilitating the local anti-tumor T-cell response." (PMID 36769082, 2023). "For instances, CCL19 could suppress tumor angiogenesis by promoting miR-206 expression dependently on CCR7, and thereby inhibiting the Met/ERK/Elk-1/HIF-1α/VEGF-A pathway." (PMID 35770088, 2022). "A statistically significant difference was observed in the CCL19 mRNA expression level between tumor tissue (NSCLC) and control tissue (p = 0.019, Mann-Whitney U-test), with a higher CCL19 mRNA expression level in tumor tissue (median RQ: 1.052 and 0.709, respectively)." (PMID 35160116, 2022). "In particular, memory CAR-T cells may infiltrate into sites with high CCL19 concentration to augment the suppressive effects in the tumor." (PMID 35990619, 2022). "Therefore, targeting the CCL19/CCL21/CCR7 axis to inhibit lymphatic metastasis but maintaining a robust antitumor immune response has increasingly become a bright spot in tumor immunotherapy." (PMID 35702353, 2022). "Higher CCR7 and CCL19 mRNA expression levels were observed in tumor tissue compared to control." (PMID 35160116, 2022). "Overexpression of CCL19 exhibited an important role in anti-tumor activity and tumor clearance." (PMID 36581948, 2022). "The result showed that CCL19 was highly expressed in tumor than in mesenchyme." (PMID 35550569, 2022). "Moreover, the interaction between calreticulin and toll-like receptor 4 (TLR4) expressed on tumor cell surface promotes the secretion of TNFα and CCL19, which facilitates the migration and maturation of DCs, to limit the tumor progression in vivo." (PMID 36703971, 2022). "Furthermore, these cells can precisely release CCL19 in the tumor tissues to recruit additional memory T cells, including memory CAR-T cells, to infiltrate inside the PC tumor tissues for enhancing the tumor suppressive effects." (PMID 35990619, 2022). "Moreover, the intravenous (IV) administration of MSLN-redirected CCL19-IL-7 CAR-Ts into a patient with advanced PC led to complete tumor elimination 240 days after the therapy." (PMID 35634281, 2022). "Both groups of CAR-T cells expressing CCL19 showed rapid infiltration in the tumor tissues." (PMID 35990619, 2022). "Moreover, it was reported that mesothelin-redirected CCL19-IL-7 CAR-Ts mediated meaningful suppression of tumor outgrowth in mice PDX models of mesothelin-expressing pancreatic cancers as compared with conventional CAR-Ts." (PMID 35634281, 2022). "However, CCL19 seemed to be the most potent anti-tumor chemokine among the four if considering results from both CT26 and MC38 models." (PMID 36654820, 2022). "In conclusion, the level of CCL19 expression is related to tumor size." (PMID 34603645, 2021). "The expression of CCL19 within the tumor could be effectively promoted by intratumor injection of AAV-CCL19." (PMID 34527749, 2021). "Since rAAV cannot replicate in vivo and therefore cannot migrate to other locations after infecting tumor cells, the CCL19 expression mediated by AAV-CCL19 might be more chemotactic compared with that mediated by CAR-T." (PMID 34527749, 2021). "Interestingly, while the upregulation in tumors is markedly higher for CCL4 and CXCL2, the CCL2, CCL8 and CCL19 transcripts are relatively downregulated in tumors compared to tumor-adjacent tissue." (PMID 34885960, 2021). "Increased mRNA expression of ADAMTS1, CCL19, and CXCL12 was associated with peritoneal metastasis, suggesting that these genes related to the tumor microenvironment may play a significant role in tumor progression." (PMID 34830815, 2021).